FAM111B (FAM111 trypsin like peptidase B)
Diseases named in the same sentence as FAM111B in open-access papers (continued):
Sharing a sentence is not in itself a finding about the gene and the disease.
cancer (continued). "Our research also demonstrated that FAM111B is negatively correlated with Th1 CD4+ T cells and positively correlated with Th2 CD4+ T cells across various cancers, indicating its role in shifting the balance of these cell populations." (PMID 40243892, 2025). "In this study, we demonstrated that FAM111B expression correlates with 17 HR repair proteins, including ATM, ATR, and BRCA1/2, in 30 out of 33 of the studied cancers." (PMID 40243892, 2025). "Additionally, bioinformatics analysis suggests that elevated expression of FAM111B augments sensitivity to chemotherapeutic drugs such as cisplatin, paclitaxel, and gemcitabine—indicating potential therapeutic strategies for targeting FAM111B in cancer treatment." (PMID 40781291, 2025). "FAM111B contains a putative trypsin-like cysteine/serine peptidase domain (TPD) at the C-terminus, which is involved in protein‒protein interactions and cancer-promoting mechanisms." (PMID 40855067, 2025). "This review highlighted the recent proposed cellular functions of the FAM111B protein to provide insights into the molecular basis of FAM111B protein dysregulation in POIKTMP and cancers." (PMID 35860584, 2022). "Another possible explanation is that FAM111B/FAM111A-repair machinery confers some advantage to cancer cells at later stages of cancer, thus supporting cancer progression." (PMID 35860584, 2022). "LINC00460 and LINC00525 were upregulated in LUAD, which improved the levels of FAM111B and ZWINT via hsa-mir-338 sponge, thus promoting the occurrence of cancer." (PMID 35406786, 2022). "LINC00460, LINC00525, FAM111B and ZWINT were upregulated and hsa-miR-338 was downregulated in most cancers." (PMID 35406786, 2022). "Similar associations with ERG have also been found for other FAM members, including FAM77C and FAM13A that are up regulated in the presence of ERG, or for FAM111B, FAM3B and FAM124B that are down-regulated in ERG positive cancers." (PMID 28415558, 2017). "Nonetheless, the potential pan-cancer implications of FAM111B have not been systematically investigated." (PMID 40243892, 2025). "Thus, our results suggest that FAM111B aids DNA repair and influences Th1/Th2 differentiation in CD4+ T cells, potentially contributing to cancer development across various types." (PMID 40243892, 2025). "This study, which also involved the in-silico analysis of FAM111B RNA expression in cancerous and non-cancer cell lines, showed that 68% of cancerous and 32% of non-cancer cell lines significantly expressed this gene." (PMID 38474092, 2024). "FAM111B, ZWINT and CDK1 have been shown to play important roles in the development of many cancers." (PMID 35406786, 2022). "Although there are about 19 reported FAM111B mutations to date, the physiological function(s) of the FAM111B protein and its dysfunctional role in diseases like fibrosis and cancers are not well established." (PMID 35860584, 2022). "Therefore, the overexpression of FAM111B and the non-specific degradation of DNA-associated proteins may cause genomic instability and dysregulation of the cell cycle, eventually contributing to cancer predisposition, development, and progression." (PMID 35860584, 2022). "It has been proposed that the promotion of cancer progression by FAM111B overexpression could be due to its role in the nonspecific proteolytic degradation of DNA-associated proteins, leading to compromised genome stability and altered cell cycle control." (PMID 40390043, 2025). "However, this contradicts the pan-cancer analysis, which suggests that FAM111B gene has no significant impact on the overall survival of BLCA patients." (PMID 37958297, 2023). "Moreover, bioinformatics and experimental studies imply high FAM111B mRNA and protein expressions in epithelial cells/tissues of cancer and non-cancerous tissues." (PMID 35860584, 2022).
cancer (continued). "Furthermore, immune infiltration analysis suggested FAM111B/ZWINT could affect the development and prognosis of cancer by regulating the LUAD immune microenvironment." (PMID 35406786, 2022).
tumor (16 papers, 2021 to 2025). "In this study, we used bioinformatics analysis based on data derived from the TCGA database to examine the association between FAM111B expression and the tumor microenvironment." (PMID 40564014, 2025). "An analysis of 33 different tumor types within the TCGA database also indicated a significant association between FAM111B and the MYC pathway in the majority of tumors (28/33) (P < 0.05)." (PMID 40781291, 2025). "Further analysis showed that FAM111B is significantly positively correlated with DNAss in 11 tumor types and RNAss in 26 tumor types, indicating an association with more aggressive tumor behavior." (PMID 40243892, 2025). "Subsequently, we examined the relationship between FAM111B expression levels, the densities of various immune cell subtypes within tumor tissues, and OS in OC patients." (PMID 40564014, 2025). "Collectively, these results demonstrate the potent and tumour-specific therapeutic efficacy of sGLNP-mediated FAM111B silencing, underscoring its translational promise for precision HCC therapy." (PMID 40855067, 2025). "Correlation between FAM111B expression and immune cell infiltration in total, tumor, and stromal tissues." (PMID 40564014, 2025). "Concurrently, the increased expression of FAM111B in tumor tissues was significantly correlated with reduced OS in OC patients." (PMID 40564014, 2025). "To investigate FAM111B’s role in the tumor immune microenvironment, we examined its correlation with the infiltration of 64 immune cell types using TCGA data." (PMID 40243892, 2025). "The relationships between FAM111B expression and the infiltration levels of different immune cell types across total, tumor, and stromal tissues were next analyzed." (PMID 40564014, 2025). "To examine the potential role of FAM111B in facilitating the EMT process during tumor progression, we assessed the expression levels of key EMT biomarkers in ES-2 and A2780 cells." (PMID 40781291, 2025). "To assess the impact of FAM111B silencing on tumor growth in vivo, we established a BALB/c nude mouse xenograft model with shFAM111B or shCtrl ES-2 cells." (PMID 40781291, 2025). "Our analysis showed that FAM111B was significantly upregulated in the high-expression cluster compared to the low-expression cluster across all four tumor types (all p < 0.05)." (PMID 40243892, 2025). "In tumor tissues, the group expressing high levels of FAM111B exhibited significantly higher CD8+ T cell, CD4+ T cell, Treg, CD4+ Teff cell, M1 macrophage, neutrophil, and DC infiltration." (PMID 40564014, 2025). "WB and qPCR analyses indicated a marked increase in FAM111B mRNA and protein levels in tumor tissues relative to adjacent normal tissues." (PMID 40390043, 2025). "The precise function of FAM111B is not fully understood, although its increased expression in tumours suggests a role in cell cycle regulation." (PMID 40840166, 2025). "For additional verification, we categorized the tumor samples into FAM111B high- and FAM111B low-expression groups and conducted GSEA analysis using the Wikipathway database." (PMID 40243892, 2025). "To further explore the relationship between FAM111B and the anti-tumor immune microenvironment, we conducted multiplex immunofluorescence experiments using tissue microarrays from 125 OV patients." (PMID 40243892, 2025). "In this study, we investigated the expression of FAM111B gene in tumor tissues compared to para-tumor tissues using immunohistochemistry and observed a significantly higher FAM111B gene expression in tumor tissues." (PMID 37958297, 2023). "Initially, we performed an immunohistochemical analysis to compare the difference in FAM111B gene expression levels between tumor and para-tumor tissues." (PMID 37958297, 2023). "The FAM111B gene expression was significantly elevated in tumor tissues, which was consistent with the results observed in The Cancer Genome Atlas (TCGA)." (PMID 37958297, 2023).
tumor (continued). "DNMT3B-mediated methylation decreases the expression of FAM111B gene, which consequently promotes tumor growth and metastasis." (PMID 37958297, 2023). "More importantly, the effect of SGI-1027 treatment on tumor growth was significantly abrogated under FAM111B knockdown." (PMID 35864964, 2022). "Notably, sGLNP efficiently silenced the expression of FAM111B and suppressed tumour proliferation in vivo." (PMID 40855067, 2025). "Additionally, FAM111B expression correlated with higher pathological grades in six tumor types (GBMLGG, LGG, UCEC, HNSC, LIHC, PAAD) and higher TNM stages in eight tumor types (LUAD, BRCA, KIRP, KIRPN, KIRC, LIHC, MESO, KICH)." (PMID 40243892, 2025). "Targeting FAM111B in HCC could inhibit tumour progression and increase lenvatinib treatment sensitivity by inducing damaged mitophagy." (PMID 40855067, 2025). "Interestingly, EPB41L3 and FAM111B proteins play contrasting roles in tumorigenesis with EPB41L3 acting as a tumour suppressor, while FAM111B functioning as a protooncogene, although recent research has challenged this view." (PMID 40840166, 2025). "Collectively, these findings suggest that FAM111B overexpression is predominantly positively correlated with the infiltration level of M1 macrophages, thereby contributing to anti-tumor immunity within total and tumor tissues." (PMID 40564014, 2025). "Furthermore, we demonstrated that FAM111B promotes the transition from Th1 to Th2 cells, thereby suggesting a mechanism for contributing to tumor immune evasion." (PMID 40243892, 2025). "Additionally, within the tumor microenvironment, we observed a correlation between FAM111B and CD4+ T cells in the OV tissue microarrays; however, our analysis did not distinguish between specific subtypes, such as Th1 and Th2 cells." (PMID 40243892, 2025). "Although the FAM111B gene promotes the progression of various solid tumors, its specific function within the tumor immune microenvironment (TIME) of OC remains unclear." (PMID 40564014, 2025). "Conversely, other investigations propose a divergent role for FAM111B as a tumour suppressor." (PMID 40840166, 2025). "FAM111B-positive cells were predominantly localized within the tumor tissues." (PMID 40564014, 2025). "The results revealed that FAM111B mRNA expression is upregulated in 21 tumor types." (PMID 40243892, 2025). "We eventually validated the role of FAM111B gene in tumor growth in mice by xenograft experiments." (PMID 37958297, 2023). "Moreover, tumor tissues exhibited higher IHC scores than their paired adjacent tissues (p < 0.001), indicating the upregulation of FAM111B gene expression in tumor tissues." (PMID 37958297, 2023). "In vivo experiments further validated that FAM111B knockdown suppressed tumor growth." (PMID 37958297, 2023). "EMT feature analysis suggested that FAM111B/ZWINT promoted tumor spread through the EMT process." (PMID 35406786, 2022). "As expected, FAM111B knockdown remarkably accelerated PTC tumor growth." (PMID 35864964, 2022). "Moreover, the knockdown effect of FAM111B was reversed by FAM111B re-expression to control the tumor xenograft growth." (PMID 35864964, 2022). "Consequently, we hypothesize that elevated FAM111B expression may modulate the anti-tumor immune microenvironment, thereby facilitating tumor malignancy progression." (PMID 40243892, 2025). "However, our analysis also revealed a significant positive correlation between FAM111B expression and the infiltration levels of Tregs, which may attenuate antitumor immune responses and promote tumor progression." (PMID 40564014, 2025). "The expression of FAM111B and the infiltration of immune cells, including CD8+ T cells, DCs, M1 macrophages, M2 macrophages, and neutrophils, were significantly higher in OC tumor tissues compared to stromal tissues." (PMID 40564014, 2025).
tumor (continued). "We detected a correlation between elevated levels of FAM111B expression and the increased infiltration of CD8+ T cells, CD4+ T cells, and CD4+ Teff cells in both total and tumor tissues by the mIF technique." (PMID 40564014, 2025). "Inhibition of FAM111B gene expression results in decreased BLCA cell proliferation and tumor growth." (PMID 37958297, 2023). "To investigate the expression pattern of FAM111B gene in BLCA tissues, we obtained a total of 66 samples (56 tumor tissues and 10 para-tumor tissues) from 56 patients with BLCA." (PMID 37958297, 2023). "The validation part demonstrated that ADAMTSL4, DOCK6, FAM111B, and SEMA6B were expressed at higher levels in the tumor tissue, whereas lower expression of MRPS10 and PSMB7 was observed." (PMID 36761753, 2023). "Consistent with the WGCNA results, in the GSE15471 dataset, the TSPOAP1 in the tumor group was significantly lower expressed, while the ADGRG6, GPR87, FAM111B and MMP28 were significantly higher expressed compared with the normal group." (PMID 34809653, 2021). "The present data indicate that FAM111B plays a central role in facilitating malignant cellular processes such as proliferation, migration, invasion, and the EMT in vitro, as well as in promoting tumor growth in vivo." (PMID 40781291, 2025). "A positive correlation between the expression of FAM111B and the infiltration levels of M1 macrophages, but not M2 macrophages, was also noted in both total and tumor tissues in this study." (PMID 40564014, 2025). "Furthermore, it has been reported that estrogen reduces FAM111B expression by DNMT3B methylation and facilitates tumor growth in PTC." (PMID 38890707, 2024). "It was suggested that FAM111B and ZWINT may promote tumor proliferation through the EMT process." (PMID 35406786, 2022). "It intimated that FAM111B and ZWINT may promote tumor spread through the EMT process." (PMID 35406786, 2022). "Moreover, many genes (PTN, SIAH2, FAM111B, TMEM43, FOSL2, TRIB1 and SPATA1) were hypomethylated regardless of tumor grade." (PMID 36850002, 2023).
myopathy (11 papers, 2015 to 2025). A disease of the muscle in which the muscle fibers do not function properly. "The gene encoding the protease family with sequence similarity 111 member B (FAM111B), which is mutated in poikiloderma with tendon contractures and myopathy (OMIM 615704), was expressed at low levels in primate capillary endothelial cells." (PMID 40555729, 2025).
genetic disorder (2 papers, 2022 to 2024). "Mutations in the FAM111B gene also lead to a genetic disorder, but the phenotypes are distinct from disorders with FAM111A mutations." (PMID 36589246, 2022). "Furthermore, heterozygous missense mutations in FAM111A and FAM111B cause distinct genetic disorders." (PMID 36589246, 2022).
infection (2 papers, 2021 to 2022). The state of being infected such as from the introduction of a foreign agent such as serum, vaccine, antigenic substance or organism. "In this report, we set out to investigate the role of FAM111B in the context of HAdV-C5 infection and the regulation of this putative cellular oncogene by HAdV-C5 E1 genes." (PMID 34071532, 2021). "While FAM111B protein levels increase early during infection, they are downregulated at later time points, likely mediated by the E3 ubiquitin ligase complex composed of E1B and E4orf6." (PMID 34071532, 2021). "Our data indicate that FAM111B acts as an anti-adenoviral host factor that is involved in host cell defense mechanisms in productive HAdV-C5 infection." (PMID 34071532, 2021). "This study demonstrates that FAM111B expression is transcriptionally activated at early times after HAdV-C5 infection." (PMID 34071532, 2021). "Here, we set out to investigate the role of FAM111B in HAdV-C5 infections." (PMID 34071532, 2021). "Taken together, our data strongly indicate that FAM111B is a novel member of a growing list of cellular restriction factors that are activated in response to HAdV infection during the immediate early phase of the infection." (PMID 34071532, 2021). "However, a recent study showed that FAM111B is upregulated after infection with human adenovirus and functions as a host restriction factor, suggesting that FAM111B might be an antiviral factor with different specificity." (PMID 36589246, 2022). "We found that (i) FAM111B levels are upregulated early and downregulated late during infection, that (ii) FAM111B expression is differentially regulated, that (iii) FAM111B expression levels depend on the presence of E1B-55K and E4orf6 and that (iv) a FAM111B knockdown increases HAdV-C5 replication." (PMID 34071532, 2021).
FAM111B also shares sentences with these, for which no sentence is quoted: pancreatic adenocarcinoma (3 papers); liver cancer (2); adenocarcinoma (1); breast invasive carcinoma (1); cervical cancer (1); epilepsy (1); fibrosis (1); glioblastoma (1); hereditary poikiloderma (1); Kenny-Caffey syndrome (1); Kindler syndrome (1); lung squamous cell carcinoma (1); male infertility (1); neurological disorders (1); ovarian tumors (1); serous carcinoma (1); systemic sclerosis (1); Werner syndrome (1).